RN7SKP239 (RN7SK pseudogene 239)
Gene: Miscellaneous RNA gene on chromosome 11 (67,362,414 to 67,362,708, forward strand). Ensembl gene ENSG00000201684.
Homologues: Orthologues: chimpanzee 7SK (98% identical). Paralogues in human: RN7SKP9 (78% identical), 7SK (77% identical), RN7SKP180 (77% identical), RN7SKP255 (77% identical), RN7SKP79 (77% identical), RN7SKP133 (76% identical), RN7SKP71 (76% identical), RN7SKP25 (76% identical), RN7SKP186 (75% identical), RN7SKP211 (75% identical), RN7SKP217 (75% identical), RN7SKP80 (75% identical), and 284 more.